PPARG (peroxisome proliferator activated receptor gamma)
Diseases named in the same sentence as PPARG in open-access papers (continued):
Sharing a sentence is not in itself a finding about the gene and the disease.
ulcerative colitis (55 papers, 2005 to 2025). An inflammatory bowel disease involving the mucosal surface of the large intestine and rectum. "Interestingly, PPARγ expression or its deficiency is primarily confined to epithelial cells and is associated with activity in ulcerative colitis." (PMID 34769138, 2021). "Gliclazide, a member of the sulfonylurea class of drugs, has demonstrated efficacy in mitigating intestinal inflammation in rats with ulcerative colitis through modulation of PPARγ, NF-κB, and MAPK signaling pathways in preclinical studies." (PMID 38835788, 2024). "In patients with ulcerative colitis, PPARG is often substantially downregulated in their colonic epithelial cells." (PMID 37503080, 2024). "Balsalazide and mesalamine are aminosalicylate drugs (DMARDs) commonly used to treat ulcerative colitis by targeting peroxisome proliferator activated receptor gamma (PPARG)." (PMID 37503080, 2024). "PPARG (PPARγ), a new coming experiment targeting the treatment of ulcerative colitis, is one of the isoforms of nuclear PPAR receptors that belong to the steroid receptor superfamily." (PMID 34997010, 2022). "Clinically, the PPARγ agonist rosiglitazone showed therapeutic efficacy in patients with ulcerative colitis." (PMID 36614012, 2022). "There was a significant activation of the NF-κB pathway, increased TLR4 expression, and reduced peroxisome proliferator-activated receptor-γ (PPARγ) expression in ulcerative colitis." (PMID 36079895, 2022). "From a pathophysiological point of view, PPARγ is downregulated in colonic epithelial cells from ulcerative colitis patients." (PMID 35431918, 2022). "Biopsies from ulcerative colitis patients with gut inflammation showed decreased expression of PPARγ in their inflamed colon." (PMID 32775340, 2020). "Taken together, PPARγ agonists seem to have some implications in the treatment of certain infectious or inflammatory diseases, including malaria, ulcerative colitis, psoriasis, and septic shock." (PMID 31614690, 2019). "In the colon, PPARγ play a key role in the control of intestinal inflammation such as ulcerative colitis." (PMID 31540047, 2019). "In both active and inactive ulcerative colitis and Crohn’s disease, the amount of PPARγ and TOLLIP were attenuated at both transcription and translation levels." (PMID 31011554, 2019). "Since PPARγ is decreased in IBDs such as ulcerative colitis and Crohn’s disease and it has been shown that Se can increase both PPARγ and its ligand 15d-PGJ2, it is plausible that under supplemented Se status, the disease would be significantly decreased." (PMID 29494512, 2018). "A clinical study comparing a healthy control group with Crohn’s disease patients found that the expression of PPARγ in the intestinal tissue of patients with ulcerative colitis (UC) was significantly decreased." (PMID 29232851, 2017). "We previously demonstrated that the expression of the peroxisome proliferator activated receptor-gamma (PPARγ) is downregulated in colonic epithelial cells of patients with ulcerative colitis (UC)." (PMID 28928735, 2017). "A recent study demonstrates that Lactobacillus plantarum LR002 (LR) improves ulcerative colitis (UC) progression in mice by activating peroxisome proliferator-activated receptor gamma (PPARγ) signaling and inhibiting the Mitogen-Activated Protein Kinase (MAPK)/NF-κB pathway." (PMID 41403703, 2025). "However, disease onset of ulcerative colitis provokes inflammation of the colonic intestinal wall, showing significant downregulation of PPARγ, compared with remission mucosal tissue." (PMID 34997010, 2022). "A recent study reported that 5-aminosalicylic acid (5-ASA), a PPARγ agonist widely used as a first-line medication for the treatment of ulcerative colitis, has been shown to increase mitochondrial respiratory capacity in Caco-2 cells, which was indicative of increased mitochondrial bioenergetics." (PMID 36614012, 2022).
ulcerative colitis (continued). "Notably, PPARγ is also highly expressed in the colon, while its expression is impaired in patients with ulcerative colitis." (PMID 33820558, 2021). "Interestingly, a greater decrease of PPARγ is observed in patients suffering from ulcerative colitis when compared to patients who suffer from Crohn’s disease." (PMID 29494512, 2018). "Interestingly, the expression of PPARγ or lack thereof was mostly confined to the epithelial cells and was correlated to the activity of ulcerative colitis." (PMID 29494512, 2018). "Indeed, a clinical trial showed that short-term treatment with rosiglitazone (PPARγ agonist) is effective in patients with mild to moderately active ulcerative colitis." (PMID 25969669, 2015). "PPARγ expression is notably decreased in the colon of patients with ulcerative colitis." (PMID 25969669, 2015). "Interestingly, clinical reports indicate that PPARγ expression in colonic epithelium is impaired in ulcerative colitis patients, while its expression in inflammatory cells remains normal." (PMID 24465207, 2014). "The study found that emu oil significantly improved the inflammation level of ulcerative colitis mice, and when used in combination with glycyrrhizin, it showed a stronger regulatory effect on the expression of PPARγ and TNFα, with a synergistic effect on the regulation of PPARγ and TNFα expression." (PMID 37299569, 2023). "Furthermore, 5-ASA, a PPARγ agonist and widely used as a first-line medication for the treatment of ulcerative colitis, has been shown to increase the spare mitochondrial respiratory capacity in Caco-2 cells, indicative of increased mitochondrial bioenergetics." (PMID 36614012, 2022). "From a molecular mechanistic perspective, the expression of peroxisome proliferator activated receptor gamma (PPARγ), a key gene with anti-inflammatory (peripheral, intestinal and neuroinflammation) and anti-dysbiotic effects is considerably reduced in ulcerative colitis and celiac disease patients." (PMID 32751379, 2020). "UMB ameliorated acetic acid-induced ulcerative colitis by modulating TLR4/NF-κB-p65/iNOS and SIRT1/PPARγ signaling pathways." (PMID 37483618, 2023). "Studies using human subjects revealed that colon biopsies from two patient groups showed lower PPARγ mRNA expression in both UC and CD samples and higher PPAR mRNA expression in patients with ulcerative colitis." (PMID 34769138, 2021). "For example, in biopsies from patients with ulcerative colitis, CBD treatment ex vivo reduces signs of inflammation that can be blocked with a PPARγ antagonist." (PMID 30720730, 2019). "5-Aminosalicylic acid (5-ASA), a peroxisome proliferator-activated receptor gamma (PPAR-γ) agonist, is a widely used first-line medication for the treatment of ulcerative colitis, but its anti-inflammatory mechanism is not fully resolved." (PMID 33468700, 2021). "Indeed, the expression of PPARγ was tremendously suppressed in the inflamed intestinal mucosa, whereas TZD-dependent PPARγ activation could exert a local anti-inflammatory effect in the gut to treat ulcerative colitis." (PMID 31614690, 2019).
glioblastoma (50 papers, 2008 to 2026). The most malignant astrocytic tumor (WHO grade IV). "High PPARγ expression is linked to poor overall survival and disease-free survival of glioblastoma patients." (PMID 40097417, 2025). "Dysregulation of lipid metabolism in glioblastoma is associated with several regulators, particularly PPARα, PPARγ, LXR, and SREBP-1." (PMID 40097417, 2025). "Based on our current understanding, there is a notable absence of comprehensive and in-depth studies exploring the molecular mechanisms underlying the regulation of PPARγ and ferroptosis in glioblastoma." (PMID 37554158, 2023). "A meta-analysis identified an association of PPARG c.1347 C > T polymorphism with elevated risk of developing malignancies such as glioblastoma and esophageal cancer." (PMID 32039832, 2020). "The PPARG rs3856806 C>T polymorphism was also found to be significantly over-represented in sporadic glioblastoma multiforme in American populations." (PMID 30838172, 2019). "In a subgroup analysis by cancer type, PPARG c.1347C>T polymorphism was associated with risk of esophageal cancer and glioblastoma." (PMID 29254243, 2017). "Moreover, PPARG is associated with increased cancer risk, even in esophageal cancer, glioblastoma, and epithelial tumor subgroups." (PMID 35154340, 2021). "In conclusion, this case-control study in Eastern Chinese Han populations, along with a comprehensive meta-analysis, identify the association of PPARG c.1347C>T polymorphism with an increased risk of cancer, even in Asians, esophageal cancer, glioblastoma and epithelial tumor subgroups." (PMID 29254243, 2017). "In this proof of principle study, we have shown that a clinically applicable PPARγ antagonist (GW‐9662) has inhibitory effects on neuroblastoma and glioblastoma cell lines." (PMID 39679632, 2024). "We raised the potential involvement of PPARγ agonists in the context of glioblastoma and tumor-related edema." (PMID 37554158, 2023). "PPARγ regulates fat metabolism, energy homeostasis, proliferation, and inflammation, and its presence is found in a variety of cancer cells, including glioblastoma." (PMID 36362294, 2022). "For example, PPARγ was reported to induce the production of reactive oxygen species to promote tumor growth in glioblastoma." (PMID 35690612, 2022). "Telmisartan in glioblastoma: Telmisartan was cytotoxic via peroxisome proliferator-activated receptor gamma (PPAR-γ) agonism in glioblastoma cells in vitro, at low concentrations." (PMID 35626167, 2022). "Panigrahy and colleagues demonstrated PPARγ expression in tumor endothelium, reduced tumor growth and metastatic spreading of subcutaneously implanted LLC1, glioblastoma, liposarcoma, and rhabdomyosarcoma upon treatment with the PPARγ agonist rosiglitazone." (PMID 32785018, 2020). "First, we found that PPARγ was exclusively expressed in MES glioblastoma stem cells (GSCs), and ligand activation of endogenous PPARγ suppressed cell growth and stemness in MES GSCs." (PMID 32280134, 2020). "β-caryophyllene is a natural CB2 receptor agonist that potentially inhibits cell survival proteins and also modulates the activation of NFκB and PPARγ; thus, it has been tested to reduce proliferation and activate apoptosis in glioblastoma." (PMID 32340197, 2020). "CLA and PPARγ synthetic agonist induced a significant increase of GFAP protein levels as well as the acquirement of the astrocytic phenotype indicating that activated-PPARγ induces differentiation of glioblastoma cells." (PMID 22091432, 2011). "CLA and PPARγ agonist suppress proliferation and induce apoptosis in primary cultures of glioblastoma cells." (PMID 22091432, 2011). "Both CLA and PPARγ agonist lead to a significant decrease of the VEGF isoforms and NOSII, thus indicating that even in glioblastoma PPARγ is able to inhibit the angiogenic pathways." (PMID 20339586, 2010). "Earlier studies have shown that PPARγ agonists induce growth arrest and apoptosis in glioblastoma cells in culture." (PMID 19018263, 2008).
glioblastoma (continued). "Many authors have documented induction of differentiation and apoptosis by ligands of PPARγ, particularly in non-small cell lung cancer, glioblastoma, prostate, colon, pituitary and liver cancer cells." (PMID 18261208, 2008). "PPARγ is highly expressed in the mesenchymal (MES) subtype glioblastoma." (PMID 40097417, 2025). "Earlier, sodium propionate was shown to promote apoptosis and autophagy pathways through a peroxisome proliferator activated receptor gamma (PPAR-γ)-dependent mechanism suggesting that the PPAR-γ/SCFAs axis could be targeted for the glioblastoma management." (PMID 39478962, 2024). "Using variable concentrations (E:T ratios) of GW‐9662 with CIK cells, we found that the CIK cells exert cytotoxic effect in both glioblastoma and neuroblastoma cells which is further enhanced significantly owing to the synergistic effect of the PPARγ inhibitor (p ≤ 0.0001)." (PMID 39679632, 2024). "Particularly in the context of CNS diseases, several studies have supported the hypothesis of using PPARγ agonists in neuroblastoma and glioblastoma." (PMID 39679632, 2024). "Likewise, the expression of FABP7 in glioblastoma cells promotes cell migration by a mechanism involving increased expression of inflammatory markers and downregulation of PPARγ signaling." (PMID 37688656, 2024). "In a clinical trial, an extended median survival of 19 months has also been reported for diabetic patients with glioblastoma who received additional treatment with PPARγ agonists, compared to 6 months of extended survival for patients receiving the standard treatment." (PMID 37554158, 2023). "Furthermore, PPARγ expression was found to be significantly elevated in mesenchymal glioblastoma, which suggested the potential use of PPARγ as a therapeutic target." (PMID 35565236, 2022). "We also found that A172 and U87 glioblastoma cells express PPARγ using western blotting analysis." (PMID 28642874, 2017). "There has been interesting preliminary evidence suggesting that diabetic patients receiving peroxisome proliferator-activated receptor gamma (PPARγ) agonists, a group of anti-diabetic, thiazolidinedione drugs, have an increased median survival for glioblastoma." (PMID 24672773, 2014). "It has been reported that PPARγ natural and synthetic ligands may interfere with glioblastoma growth and malignancy and might be taken in account as novel antitumoral drugs." (PMID 22091432, 2011). "Recent studies have shown that peroxisome proliferator-activated receptor gamma (PPARγ) agonists induce growth arrest and apoptosis in glioblastoma cells, but their effects on BTSCs are largely unknown." (PMID 19018263, 2008). "The regulation of lipid metabolism by both PPARα and PPARγ plays a crucial role in shaping the biological behavior of glioblastoma, which is involved in lipid homeostasis and cellular signaling, and presents promising avenues for therapeutic intervention in glioblastoma." (PMID 40097417, 2025). "To test our hypothesis that combined treatment with PPARγ ligands and the PPARγ inhibitor GW9662 (GW) yields a more favorable antiproliferative effect in glioblastoma spheres compared to single-agent treatments, we first examined its effects on cellular viability." (PMID 28642874, 2017). "QA acts as a metabolic checkpoint in glioblastoma by inducing NMDA receptor activation and Foxo1/PPARγ signaling in macrophages, resulting in a tumor supportive phenotype." (PMID 36927729, 2023). "Similarly, icaritin (a hydrolytic product of the natural product icariin) was found to induce cell cycle arrest and apoptosis in glioblastoma multiforme (GBM) by activating PPARγ." (PMID 34944727, 2021). "Both CLA and PPARγ agonist treatments led to a significant decrease of the VEGF isoforms and NOSII, thus indicating that even in glioblastoma, PPARγ is able to inhibit the angiogenetic pathways." (PMID 22091432, 2011).
glioblastoma (continued). "Conjugated linoleic acid (CLA) and the PPARγ synthetic agonist GW347845 also suppress proliferation and induce apoptosis in primary cultures of glioblastoma cells." (PMID 20339586, 2010). "PPARγ activation suppresses proneural-mesenchymal transition process by reducing the STAT3 signaling pathways and suppresses the growth and stemness of MES glioblastoma stem cells (GSCs)." (PMID 40097417, 2025). "We investigated neuroblastoma and glioblastoma cell lines with mature CIK cells and the PPARγ antagonist GW‐9662 to assess the effects on cell viability, candidate gene expression (Wnt/β‐catenin signalling, DNMT1) and global methylation levels (5‐methylcytosine, LINE‐1)." (PMID 39679632, 2024). "However, the trans-differentiation of glioblastoma multiforme (GBM) cancer stem cells into adipocyte-like cells was induced by morusin treatment, in which the expression of adipogenic proteins including PPARγ, Adipsin D and aP2 were enhanced in a dose-dependent manner." (PMID 32906784, 2020). "Combination of PPARγ and RAR ligands led to cell-cycle arrest in human glioblastoma cell line." (PMID 24098526, 2013). "Earlier studies have shown that PPARγ agonists induced growth arrest and apoptosis in glioblastoma cells without affecting primary astrocytes, demonstrating its anti-neoplastic potency in humans." (PMID 19018263, 2008). "Also, it was shown that Interleukin-13 (IL-13) induces the 15-LOX-1 expression and activity that resulted in the elevation of 15-LOX-1 metabolites, activation of peroxisome proliferator-activated receptor-gamma (PPAR-γ), initiation of apoptosis in glioblastoma cells." (PMID 34838055, 2021). "In clinical assessment, diabetic patients with glioblastoma treated with PPARγ agonists showed a longer median survival of 19 months, compared to 6 months in similar patients receiving the standard GBM treatment PPARγ ligands could therefore be a potential drug for the treatment of glioblastoma." (PMID 36362294, 2022).